CCL5 (C-C motif chemokine ligand 5)
Diseases named in the same sentence as CCL5 in open-access papers (continued):
Sharing a sentence is not in itself a finding about the gene and the disease.
tumor (continued). "Taken together, chemokines such as XCL1, CCL4, and CCL5 secreted by NK cells and activated T cells within the TME recruit cDC1s into the tumor where they efficiently process antigens and then migrate to lymph nodes while they undergo maturation." (PMID 33679726, 2020). "Cancer cells stimulate CCL5 secretion by MSCs, and MSC-derived CCL5 promotes tumor cell invasion and MMP activation." (PMID 32630699, 2020). "In our study, our results also revealed that compared with normal lung epithelial cells, CCL5 and CXCL13 had higher expressions in tumor cells." (PMID 32549766, 2020). "The coculture of THP-1-derived macrophages with GC cells up-regulated CCL5, MMP2, and MMP9 in THP-1 cells, and increased tumor cell proliferation, clonogenic growth and migration." (PMID 32630699, 2020). "Tumor size, degree of tumor invasion, lymphatic metastasis and pathological grading correlate with high levels of CD68 and CCL5." (PMID 32630699, 2020). "Specifically, first, tumor cells secrete a large number of chemokines to recruit macrophages into tumor tissues, such as CCL2, CCL3, CCL5, and so on." (PMID 33224886, 2020). "The results of correlation analysis between the expression of significant genes and tumor-infiltrating immune cells showed that the expression of CCL5, CCL8, CCR4, and CCR5 were all correlated with the level of tumor immune cell infiltration." (PMID 33181717, 2020). "CCL5 induces MMP-9 secretion and collagen degradation by monocytes, supporting tumor cell extravasation." (PMID 32630699, 2020). "MSC pre-treated with cisplatin increased CCL5 expression and phosphorylation of tyrosine kinases (PLC, WNK1, c-Jun, STAT3), possibly playing roles in tumor cell changes, as witnessed in breast cancer cells." (PMID 32499779, 2020). "This interactive loop gave rise to increased metastasis in mice that were administered with tumor-MSC co-cultures, through osteopontin and CCL5-dependent mechanisms." (PMID 32582148, 2020). "Significantly, CX3CL1 is not the only chemokine involved in this process, e.g., also important in the recruitment of microglia to GBM tumor are MCP-1/CCL2 and RANTES/CCL5." (PMID 32466280, 2020). "Many preclinical studies in different cancer models have demonstrated the protumorigenic role of the CCL5/CCR5 axis, which is involved not only in tumor growth and metastasis but also in the formation of an immunosuppressive and protective TME." (PMID 32630699, 2020). "It has been shown that CX3CR1+ monocytes are recruited to the tumor cell aggregates in response to tumor-derived CX3CL1, where they can directly engage cancer cells or secrete CCL3, CCL4 and CCL5 to activate natural killer cells to kill CTCs." (PMID 33414786, 2020). "Previous studies determined the upregulation of genes related to immune cell activation (e.g., CD3D, CD8, CXCR3, CCL5, CXCL9, and CXCL10) in cancer patients with a better prognosis, thereby highlighting the impacts of immune-related genes on tumor progression." (PMID 32775427, 2020). "The results of this study therefore support the idea that CCL5 together with CCR5 plays an important role in the recruitment of immune cells to tumour sites and ultimately delays tumour growth." (PMID 32098198, 2020). "Hyper-activated STAT3 regulates the expression of interferon γ (IFNγ), interleukin 12 (IL-12), CD86, C-C motif chemokine ligand 5 (CCL5), and C-X-C motif chemokine ligand 10 (CXCL10) in the tumor microenvironment to promote immune evasion." (PMID 32486001, 2020). "In parallel, CCL2 activities via CCR2, as well as CCL5-induced signaling were demonstrated to contribute to increased EMT and twist expression, at times accompanied by increased tumor cell invasion in breast cancer cells." (PMID 32582148, 2020). "Further research needs to perform to investigate the expressions of CCL5 and CXCL13 in tumor and T cells." (PMID 32549766, 2020).
tumor (continued). "In pre-metastatic organs, CCL5 formed a chemotactic gradient to recruit CCR5-positive cancer cells and thus facilitated tumor cell dissemination." (PMID 32630699, 2020). "Since both CCL5 and CXCL10 attract CD8+ T cells into tumor sites, we next analyzed the effect of CD8 on the survival of patients from TCGA datasets." (PMID 31221150, 2019). "CCL2, CCL5 and IDO play key roles in promoting tumor growth and progression partially by inhibiting the immune response against cancer through Tregs." (PMID 30808421, 2019). "The tumor-stroma-inflammation network was found in our study to strongly induce the expression of the pro-metastatic chemokines CXCL8, CCL2 and CCL5." (PMID 31031757, 2019). "Three fractions of RT increased the concentrations of seven inflammatory mediators in tumor tissues: GM-CSF, IL-17, CXCL1, CXCL2, CCL2, CCL5 and TNFα." (PMID 31752313, 2019). "Chemokine receptors CCR1 and CCR5 are expressed on monocytes and facilitate their recruitment under chemotactic gradient of CCL5 and CCL731 and play a crucial role in tumor progression." (PMID 30850664, 2019). "We demonstrated that human MSCs secreted high levels of CCR5 ligands (i.e., CCL3, CCL4, and CCL5), and that MSCs promoted CRC tumor growth in vivo via CCR5 signaling." (PMID 30890699, 2019). "Microglial gliomagens include chemokines, growth factors and inflammatory mediators; among a series of candidate molecules, Ccl5 was found enriched in murine OPG and treatment with Ccl5 neutralizing antibodies reduced tumor growth in mice." (PMID 31739524, 2019). "In this study, we found that the expression of CCL5, CXCL9, and CXCL11 was increased in tumor cells after irradiation." (PMID 31921127, 2019). "In addition, CCL5 has been shown to increase αvβ3 integrin expression in cancer cells and increase NF-κB-mediated resistance to drug-induced apoptosis, thus facilitating enhanced integrin-mediated tumor invasion and an immunosuppressive, anti-apoptotic tumor microenvironment." (PMID 31191817, 2019). "In our study, we also showed that IFN-I signature genes were closely associated with T cell infiltration including T cell marker CD8 and chemokines CCL5 and CXCL10 recruiting T cells to tumor sites." (PMID 31221150, 2019). "Studies show that along with CCL5, CCL3 mediated fibroblast accumulation in the tumor microenvironment." (PMID 31835892, 2019). "CCL5 expression is activated by NOTCH signaling in the tumor microenvironment, both in cancer cells and tumor infiltrating lymphocytes." (PMID 31921621, 2019). "Work by Peng's group showed that tumor-derived fibroblasts secreted MCP-1 (known as CCL2), the ligand for CCR2 or CCR4, and RANTES (known as CCL5), the ligand for CCR1, CCR3, or CCR5." (PMID 30800130, 2019). "HS-EVs were also shown to contain the chemokines CCL2, CCL3, CCL4, CCL5, and CCL20, which chemoattracted CD11c+ DCs and CD4+/CD8+ T cells into tumor tissues in vivo." (PMID 31680949, 2019). "FAP+ CAFs modulate the tumor microenvironment through secretions such as C-C motif chemokine ligand 1, 2 and 5 (CCL1, CCL2, CCL5) and CXCL12 in HCC." (PMID 31540435, 2019). "Among the others, CCL2, CCL3, and CCL5 contribute to tumor vascularization and metastasis and also stimulate MMP9 secretion by monocytes, which strongly favors tumor cell extravasation." (PMID 31484464, 2019). "MSCs are recruited to the tumor site from the bone marrow in response to soluble factors produced by tumor cells, such as IL-1, SDF-1, CCL5, and more recently the aspartic acid protease cathepsin D." (PMID 31547627, 2019). "This was indeed confirmed in the xenografts by IHC analysis, which stained tumor sections for CD8, CCL5, and CXCL10." (PMID 31221150, 2019). "CD4+ helper T lymphocytes react to CAF secretion of CCL2, CCL5, and CCL17 along with polarizing cytokines IL-1, IL-6, IL-13, and IL-26 by switching from an anti-tumor TH1 response to a pro-tumor TH2 and TH17 response." (PMID 31058816, 2019).
tumor (continued). "Cytokines and chemokines derived from tumor cells and cancer-associated fibroblasts (CAFs), such as CSF-1, CXCL12/SDF1, CCL2/MCP-1, CCL5/RANTES, and VEGF, recruit mononuclear cells into the tumor microenvironment and activate them to become TAMs or MDSCs." (PMID 31554173, 2019). "These TAMs can be derived from resident macrophages or attracted from bone marrow and spleen to the tumor site thanks to the CCL2 (MCP-1) and CCL5 (RANTES) chemokines produced by the tumors, fibroblasts, endothelial cells, and even by the TAMs themselves." (PMID 31547627, 2019). "Other mechanisms for diminishing TAM recruitment by the tumor or re-polarizing TAMs to the M1 phenotype are also being investigated, including antagonism of CCL2 and/or CCL5 or their receptors." (PMID 31921140, 2019). "We have recently demonstrated that short-term exposure of osteoblasts to pH 6.8 promotes the expression of factors that foster tumor progression, such as interleukin 6 (IL6), interleukin 8 (IL8), and the chemokine (C-C motif) ligand 5 (CCL5)." (PMID 30825056, 2019). "N2 neutrophils are characterized as a higher expression of pro-tumor factors to induce the immunosuppression in the tumor microenvironment, including CCL2, CCL5, neutrophil elastase (NE), and cathepsin G (CG), with a higher expression of arginase." (PMID 31010242, 2019). "Evidence indicates, for example, that chemokines such as CCL5, CCL7, CXCL8 act via CCRs on myeloid-derived suppressor cells (MDSCs) to form an inhibitory tumor microenvironment that promotes tumor pathogenesis, progression and resistance." (PMID 30631005, 2019). "During tumor development, cancer cells secrete chemokines such as CCL2, CCL5, CXCL12, and colony stimulating factor 1 (CSF1) to recruit immune cells towards the tumor site." (PMID 31766635, 2019). "Indeed, fully differentiated cDC1 recruited from blood or surrounding tissue might be the predominant origin of intratumoral cDC1s that accumulate in response to XCL1 and CCL5 produced by tumor NK cells because cDC1 precursors express only low levels of transcripts for CCR5 and XCR1." (PMID 30352680, 2018). "Like NK cells, T cells can be mobilized, activated, and differentiated in the senescent tumor from a variety of SASP factors including CCL27, CCL2, CCL5, CXCL11, and IL-1α." (PMID 29868482, 2018). "Here, we uncover a key role for NK cells in the production of chemoattractants, including CCL5 and XCL1/2, that are necessary for the accumulation of cDC1 in incipient tumors and for tumor immune control." (PMID 29429633, 2018). "It is also reported that a highly metastatic derivative of MDA-MB-231 cells (named BM1) expresses high levels of CCL5 (a ligand for CCR5) and treatment of BM1 tumor-bearing mice with a CCR5 antagonist significantly reduces the number of TAMs in tumors." (PMID 30483271, 2018). "To the importance of chemokine study in tumor cells, we further extend CCR5/CCL5 interaction in selected PC cell lines." (PMID 29358632, 2018). "Diverse chemokines, i.e., CCL2 (MCP-1), CCL5 (RANTES), CCL7 (MCP-3), CXCL8 (IL-8), and CXCL12 (SDF1), released by tumor cells induce migration, differentiation, and survival of tumor-infiltrating myeloid cells." (PMID 29686671, 2018). "Mɸ are recruited into irradiated tumour tissue at both acute and late stages through Mø/Mɸ chemoattractants CCL2, CCL5, CCL7, CCL8, CXCL12, VEGF and CSF-1." (PMID 30178305, 2018). "Melanoma and pancreatic tumors treated with this combination therapy express an immune stimulatory SASP, most significantly CCL5, IFN-β, and CXCL11, to promote dendritic cell proliferation and enhanced cytotoxic lymphocyte anti-tumor activity." (PMID 29868482, 2018). "TILs were correlated with residual tumor size after neoadjuvant chemotherapy (NAC) and CCL5 expression." (PMID 29559701, 2018). "Tumour-infiltrating lymphocytes were detectable throughout the E-MpM series and paralleled the coordinated expression of the CXCL9, CXCL10, and CCL5 chemokines acting in lymphocyte recruitment." (PMID 30510965, 2018).
tumor (continued). "The results revealed that the number of CD8+ T cells was decreased in the blood of CCL5−/− group compared with that of CCL5+/+ group, suggesting that there was an enhanced migration of CD8+ T cells into the tumor sites in CCL5−/− mice." (PMID 29991744, 2018). "Similar to MDSCs, TAMs and TANs are recruited to tumor sites by tumor-derived chemokines and growth factors, including CCL2/MCP-1, CXCL1/Gro-a, CCL7/MCP-3, CCL5/RANTES, CXCL8/IL-8, VEGF, PDGF, and M-CSF/CSF-1." (PMID 29735917, 2018). "CCL5 can attract T lymphocytes to the tumor, while CCL3 is able to recruit neutrophils into the tumor." (PMID 29755464, 2018). "The tumor growth rate and hepatic metastasis of CCL5−/− mice were increased after S100a9 treatment compared to CCL5−/− mice treated with PBS." (PMID 29991744, 2018). "Among the receptors of CCL5, its interaction with CCR5 was very well established and elucidated in tumor progression and recruitment of tumor infiltration leukocytes in several cancer types." (PMID 29358632, 2018). "Tumor pDC produced low quantities of IL-6, TNF-α, IFN-α, macrophage inflammatory protein-1β (MIP-1β), and RANTES (CCL5) in response to TLR stimulation, in contrast to pDC from ascites or peripheral blood." (PMID 30200478, 2018). "In the STING agonist-treated tumour-bearing mice, we foundsignificantly elevated levels of the cytokines, CXCL10, CCL5, IFN-γ, M-CSF, CXCL9and CXCL1 at early, mid and late time points in comparison to levels in plasmafrom vehicle-treated mice." (PMID 30046165, 2018). "In tumor models, neutrophils can be converted from anti-tumor phenotype (N1: release ROS and TNF-α) to pro-tumor phenotype (N2: increased Arginase, CCL2, and CCL5) by the TGF-β stimulation." (PMID 29776443, 2018). "Next, we focus on the function of CD11bhiF4/80low TAMs isolated from tumor sites of CCL5+/+ mice and CCL5−/− mice and their global transcriptional profiles were analyzed using RNA-sequencing." (PMID 29991744, 2018). "Increased expression of KLRC1, CCL5, PLP1, CD163, MSR1, and GPNMB was found following treatment and tumor recurrence." (PMID 30151353, 2018). "In an immune stimulatory tumour microenvironment, eosinophils would produce high numbers of potent chemoattractants for CD8+T cells via STAT1, such as CCL5, CXCL10, CXCL1118." (PMID 29440650, 2018). "In contrast to CCL5, which acts on the chemokine receptor CCR5 and can promote migration of tumor-promoting immune cells such as macrophages and Treg cells 32, 33, XCL1 acts as a ligand for XCR1 and acts on XCR1+ cDC1s but not on other cells." (PMID 30352680, 2018). "To further confirm the effect of CCL5 on CRC, we utilized orthotopic CT26 tumor model to verify our results." (PMID 29991744, 2018). "Here, we present more evidence that both IL-6 and CCL5 are key factors in TNBC lymphangiogenesis, tumor growth, and thoracic metastasis." (PMID 29898755, 2018). "Assessing the chemokine expression profile of tumor-residing immune cell subsets, the authors showed that XCL1 is produced exclusively by NK cells while CCL5 is secreted by both NK cells and CD8+ effector T cells." (PMID 29986768, 2018). "Since alcohol increased CCL5 secretion in HT29 and DLD-1 cells, we focused on its role in tumor cell malignant biological behaviors." (PMID 29872080, 2018). "We conclude that cDC1 accumulation within the TME can be induced by the cDC1-recruiting chemokines CCL5 and XCL1 to improve tumor immune control." (PMID 29429633, 2018). "In the TME, the presence of CAFs and their secretion of CCL2, CCL5, and CCL17 as well as the polarizing cytokines IL-1, IL-6, IL-13, and IL-26 can favor a tumor promoting TH2 and TH17 immune response, as the expense of tumor protective TH1 response." (PMID 29545811, 2018). "Efficient NK–DC interaction in the tumor can lead to increase of CXCR3 and CCR5 on DC, which can recruit CD8+ effector T cells to tumors, in the presence of chemokines CXCL9, CXCL10, and CCL5." (PMID 30200478, 2018).
tumor (continued). "In ovarian cancer, CCL5 can induce matrix metalloproteinases-9 (MMP-9) secretion by monocytes, which, by degrading the matrix, allows for tumor cell extravasation." (PMID 29772686, 2018). "Taken together, these findings show that IL-6 and CCL5 signaling, which promote crosstalk between TNBC and lymphatic vessels, are key enhancers of TNBC tumor growth and metastasis." (PMID 29898755, 2018). "A candidate‐based screen of tumor lysates and differential protein arrays of cultured HSC identified several established hepatotropic cytokines, including IGF2, RBP4, DKK1, and CCL5 as being negatively regulated by endosialin." (PMID 28373218, 2017). "The tumor-promoting effect of MSCs is attributed to the activation of epithelial–mesenchymal transition (EMT) process, which is mediated by CCL5/CCR1/β-catenin/Slug pathway." (PMID 28542126, 2017). "CAFs also secrete factors including VEGF, CXCL12, FGF, IL-8/CXCL8 and PDGF to stimulate tumor angiogenesis, CAFs release factors such as HGF, CCL5 and stanniocalcin 1 (STC1) to stimulate tumor invasiveness and metastasis." (PMID 29383119, 2017). "3xTg-AD mice had an increased pro-inflammatory response characterised by the production of pro-inflammatory mediators such as tumour necrosis TNF-α, IL-6, CCL5 and CXCL-1, as well as an increase in immune cell infiltration to the sites of infection." (PMID 28284226, 2017). "We observed that the mRNA expression of CCL5 and CCR5 as well as LTβR-related chemokines, such as CCL21, CCL19 and CXCL13 were substantially enhanced in the tumor tissue of EL4-Axl-bearing mice compared with mock control." (PMID 28423548, 2017). "Often released by tumor or macrophages for local suppression of anti-tumor immune responses, including TGF-β, CCL5, CCL7, CXCL8, IDO, etc." (PMID 29299180, 2017). "The increase in IL-6, IL-12, CCL2, CCL3, CCL5, CXCL9 levels would a priori predict for elevated levels of M1 type macrophages in the tumor, which independently validates our prior IHC staining findings." (PMID 29137331, 2017). "Tumor-derived exosomes can contribute to breast cancer development by converting adipose tissue-MSCs into tumor-associated myofibroblasts, and exosome treatment can increase the expression of tumor-stimulating molecules (SDF-1, VEGF, CCL5 and TGFβ)." (PMID 28402944, 2017). "Considering chemotactic factors, the mRNA expression of CCL5, CXCL9, CXCL16, and CCL25 was higher in HCCLM3 cells from micrometastatic regions than in cells from primary tumor sites when cocultured with MSCs." (PMID 28205428, 2017). "In tumors, chemokines such as CCL2, CCL5, IL-8, and CXCL-12 also chemoattract TAMs to the tumor site." (PMID 28545495, 2017). "Chemokines and cytokines including CCL2, CXCL12, CSF1, CCL5, CCL22, IL6 and TGFB3 are secreted by primary tumor cells to recruit immune cells to escape from anti-tumor immune responses." (PMID 28591712, 2017). "TNFα evoked release of tumor-promoting chemokines such as CCL2 (MCP-1), CCL5 (RANTES) and CXCL8 (IL-8) trigger infiltration of CCR2/CCR5 receptor bearing leukocyte sub-populations (LSPs) including TAMs, MDSCs, TANs, Tregs, MAMs and CAFs." (PMID 28441391, 2017). "The chemokine C-C motif ligand 5 (CCL5) and its receptor, CCR5 are critical regulators for the infiltration of immune cells into the tumor microenvironment." (PMID 28423548, 2017). "M-MDSC and monocytes are recruited to primary tumour sites and metastatic sites by chemokines secreted by tumour cells, most commonly CCL2 and CCL5, which function to regulate monocyte chemotaxis." (PMID 28193698, 2017). "Th2 related chemokines CCL5 and CCL22 preferentially recruit T cells that lack the capacity to eliminate tumor cells by direct lysis, i.e., regulatory T cells and Th2 cells; the latter bias immune responses away from Th1." (PMID 26943036, 2016).